METTL14 (methyltransferase 14, N6-adenosine-methyltransferase non-catalytic subunit)
Diseases named in the same sentence as METTL14 in open-access papers (continued):
Sharing a sentence is not in itself a finding about the gene and the disease.
colitis (continued). "However, only one study reports an association between m6A regulators and disease progression in IBD, and it reports that METTL14 (a “writer” gene) deficiency in T cells promotes spontaneous colitis in mice." (PMID 34422815, 2021). "T cell-specific METTL14 deficiency prevents the differentiation of naïve T cells into Tregs, leading to an imbalance in Th17 cells and Tregs, and thereby inducing spontaneous colitis." (PMID 34869344, 2021). "Additionally, in a mouse model of colitis, METTL14 deficiency in T cells increases inflammatory cell infiltration, increases cytokine release from Th1 and Th17 cells and prevents the differentiation of naïve T cells into Tregs." (PMID 34869344, 2021). "Studies support a single m6A regulator participating in the immune-associated colitis-like methyltransferase 14 (METTL14) deletion in T-cells trigger spontaneous colitis, and m6A reader ELAV-like RNA binding protein 1 (ELAVL1, also known as HuR) maintain colonic epithelial Paneth cells’ function." (PMID 35127705, 2021). "METTL14 deficiency in T cells induced spontaneous colitis in mice." (PMID 32634481, 2020). "Intriguingly, conditional knockdown of METTL14 in T cells has been found to trigger spontaneous colitis in mice." (PMID 38830900, 2024). "Selective deletion of Mettl14 in T cells impairs the induction of naïve T cells into induced Treg cells and leads to spontaneous colitis in mouse models, providing a new tool for investigating inflammatory bowel diseases (IBD) or IBD‐associated malignancy." (PMID 36794620, 2023). "Mettl14 depletion in mouse colon results in colonic stem cell apoptosis, mucosal barrier dysfunction and severe colitis by modulating the NF-κB pathway." (PMID 37872148, 2023). "This is similar to the phenotype we observed in our mice with lineage specific deletion of Mettl14 in T cells, except that our mice developed colitis as early as week 6, and the inflammation became progressively more severe over time." (PMID 32634481, 2020). "Here, we show that deletion of RNA m6A methyltransferase component METTL14 in T cells leads to spontaneous colitis." (PMID 32634481, 2020). "We aim to study how deletion of a critical component of m6A writer complex, METTL14, in T cells affects the development of colitis." (PMID 32634481, 2020). "Here, we show that deletion of Mettl14 in T cells induces development of spontaneous colitis in mice." (PMID 32634481, 2020). "Deficiency of METTL14 has been shown to promote cell apoptosis and inhibit the formation and function of mature colonic epithelial cells, leading to the development of dextran sulfate sodium (DSS)-induced colitis." (PMID 38830900, 2024). "Furthermore, the depletion of METTL14 in IECs disrupts colonic epithelial morphogenesis, resulting in the development of spontaneous colitis and systemic inflammation." (PMID 38830900, 2024). "Extensive research has revealed that METTL14 functions as a central mediator in modulating inflammatory responses across various diseases, such as coronary artery disease, psoriasis, rheumatoid arthritis, glomerulonephritis, colitis, and ankylosing spondylitis." (PMID 41316520, 2025). "Moreover, mice with specific deletion of METTL14 in CD4+ T cells developed spontaneous colitis, characterized by increased inflammatory cell infiltration along with a marked increase of Th1 cytokines (IFN-γ and TNF-α) and Th17 cytokines (IL-17a and IL-17c) in colonic epithelial." (PMID 35935968, 2022). "In a study in which palmatine (PAL) improved experimental colitis in rats, PAL significantly increased the expression levels of METTL3, METTL14, and ZO-1 and repaired intestinal barrier dysfunction." (PMID 40829428, 2025). "Furthermore, METTL14 catalyzes m6A methylation of TNFAIP3 in rheumatoid arthritis, promotes glomerulopathy progression through Sirt1 suppression, and stabilizes NF‐κB mRNA to regulate colitis." (PMID 41316520, 2025).
colitis (continued). "Studies investigating colitis pathogenesis have revealed that Mettl14-deficient Treg cells fail to adequately suppress inflammation induced by naïve T cells in a colitis model, demonstrating that the absence of METTL14 in T cells can lead to spontaneous colitis." (PMID 39199429, 2024).
clear cell renal cell carcinoma (17 papers, 2020 to 2025). "In clear cell renal cell carcinoma (ccRCC), METTL14 expression is inversely correlated with Treg abundance and positively associated with CCL5 levels, suggesting a METTL14/CCL5/Tregs axis that shapes the tumor immune landscape." (PMID 41164187, 2025). "The down-regulated METTL14 in renal clear cell carcinoma can accumulate bromodomain PHD finger transcription factor (BPTF) and cause distant lung metastasis through chromatin remodeling." (PMID 36941564, 2023). "In the clear cell renal cell carcinoma model, down-regulated METTL14 induced the overexpression of BPTF." (PMID 36967443, 2023). "This study was aimed to investigate the prognostic value of METTL14 in clear cell renal cell carcinoma (ccRCC)." (PMID 33430867, 2021). "Knockdown of METTL14 promotes ITGB4 expression via m6A-YTHDF2, stimulates EMT, and promotes migration, invasion, and metastasis in renal clear cell carcinoma cells." (PMID 36358640, 2022). "One recent study reported a signature consisting of METTL14 and METTL3 as an independent prognosis factor in clear cell renal cell carcinoma." (PMID 33363211, 2020). "A previous study found that METTL14 was down-regulated in the clear cell renal cell carcinoma (ccRCC) tissues, and the m6A level of Lnc-LSG1 could be regulated by METTL14, thereby playing important roles in ccRCC progression." (PMID 38326804, 2024). "In conclusion, we built up a three-m6A methylation regulators-based RS of METTL3, METTL14 and HNRNPA2B1 that may become potential biomarker for prognosis prediction of clear cell renal cell carcinoma patients, our results call for further experimental studies for validations." (PMID 32219036, 2020).
Obesity (17 papers, 2018 to 2025). Accumulation of substantial excess body fat. "“Writers” like METTL3 and METTL14 add m6A marks, “erasers” such as fat mass and obesity-associated protein (FTO), ALKBH5 remove them, and “readers” including YTHDF1, YTHDC1 recognize the marks, mediating functional outcomes." (PMID 40442779, 2025). "The enzymes involved in m6A RNA methylation, including methyltransferase‐like protein 3 and 14 (Mettl3, Mettl14), as well as demethylase, fat mass and obesity‐associated (FTO) were further examined." (PMID 39445711, 2024). "Given that obesity is associated with hyperinsulinemia, we tested if adipose Mettl14 and m6A are elevated in obesity." (PMID 37526326, 2023). "The phenotypes of Mettl14Δfat mice provide proof‐of‐concept evidence that Mettl14‐based epitranscriptomic inhibition of adipose β adrenergic signaling and lipolysis is a causal factor for obesity and its associated metabolic disorders." (PMID 37526326, 2023). "Taken together, these results suggest that aberrant upregulation of adipose Mettl14 and m6A modification increases risk to both obesity and obesity‐associated insulin resistance and NAFLD." (PMID 37526326, 2023). "RNAs can be methylated by Methyltransferase-like 3(METTL3), Methyltransferase-like 14 (METTL14) (“writers”), and demethylated by the fat mass- and obesity-associated (FTO) protein and the α-ketoglutarate-dependent dioxygenase alkB homolog 5 (ALKBH5) protein (“erasers”)." (PMID 35346019, 2022). "Collectively, these results suggest that upregulation of adipocyte Mettl3, Mettl14, and m6A methylation of Atgl, Cgi‐58, Adrb2, and Adrb3 transcripts causes, at least in part, adipose catecholamine resistance, lipolysis suppression, adipose expansion, and metabolic disorders in obesity." (PMID 37526326, 2023). "Hepatocyte‐specific deletion of Mettl14 decreases G6pc m6A methylation, G6pc biosynthesis, and G6pc‐mediated gluconeogenesis, alleviating glucose metabolic defects in obesity." (PMID 40278833, 2025). "Mice with adipocyte‐specific deletion of Mettl14 are resistant to HFD‐induced obesity, insulin resistance, glucose intolerance, and nonalcoholic fatty liver disease (NAFLD)." (PMID 37526326, 2023). "Collectively, these results suggest that aberrant upregulation of adipose Mettl14 and m6A modification contributes to adipose catecholamine resistance and lipolysis suppression in obesity." (PMID 37526326, 2023). "Adipocyte‐specific deletion of Mettl14 protects against diet‐induced obesity, NAFLD, and metabolic disease through increasing adipose β adrenergic signaling and lipolysis." (PMID 37526326, 2023). "Additional studies are needed to assess the contributions of hyperinsulinemia and other obesogenic factors to upregulation of adipose Mettl3, Mettl14, and m6A‐based epitranscriptomic remodeling in obesity." (PMID 37526326, 2023). "In conclusion, we propose a Mettl14/m6A‐centric epitranscriptomic reprogramming paradigm in obesity." (PMID 37526326, 2023). "Collectively, these results demonstrate, for the first time, that adipose Mettl14/m6A pathway is required for diet‐induced obesity." (PMID 37526326, 2023). "To test if adipose METTL14 similarly regulates lipolysis in human obesity, we measured expression of METTL14 expression and m6A levels in visceral WAT." (PMID 37526326, 2023). "Adipose Mettl3, Mettl14, and m6A levels are upregulated in obesity, prompting us to test if their molecular targets involved in lipolysis are downregulated in WAT." (PMID 37526326, 2023). "Although many more investigations are needed, our data collectively suggest that intervention of WTAP, METTL3, METTL14, or an undetermined target of cell cycle-related molecules is a strategy for preventing and treating obesity or obesity-related diseases." (PMID 29866655, 2018). "Liver METTL14/METTL3/m6A pathways were also activated in obesity (described later)." (PMID 40278833, 2025).
Obesity (continued). "Notably, obesity is associated with hyperinsulinemia and perhaps, elevated insulin levels are involved in upregulation of adipose Mettl14 and m6A modifications in obesity." (PMID 37526326, 2023). "Importantly, adipocyte‐specific deletion of Mettl14 blocked HFD‐induced obesity, insulin resistance, glucose intolerance, and NAFLD, accompanied by increased β adrenergic signaling and lipolysis in WAT." (PMID 37526326, 2023). "In line with this notion, transgenic expression of Atgl in adipocytes alleviates obesity and metabolic disorders.[2a] Therefore, the adipose Mettl14/m6A pathway may serve as a potential therapeutic target for treatment of obesity and related metabolic disease." (PMID 37526326, 2023). "Genetic studies of depleting either m6A methyltransferases, such as METTL3 and METTL14 or demethylase FTO (fat mass and obesity associated protein), have demonstrated their important roles in controlling cortical development and regulating brain cognitive functions." (PMID 32992647, 2020). "Liver METTL14, METTL3, and m6A‐methylated G6pc mRNA are upregulated in mice with diet‐induced obesity." (PMID 40278833, 2025). "Mettl14f/f mice were fed a HFD for 10 weeks (inducing obesity and metabolic disorders) and transduced with AAV8‐TBG‐Cre vector to specifically delete hepatic Mettl14 (AAV8‐TBG‐GFP as control)." (PMID 40278833, 2025). "Recent studies have identified that METTL14/m6A-mediated epitranscriptomic alterations disrupt ADRB signaling in adipose tissue, contributing to the development of obesity, NAFLD, and other metabolic disorders." (PMID 39640486, 2024). "Here, this work shows that adipose Mettl3 and Mettl14 are influenced by fasting, refeeding, and insulin, and are upregulated in high fat diet (HFD) induced obesity." (PMID 37526326, 2023). "Adipocyte‐specific deletion of Mettl14 increases adipose lipolysis and protects against HFD‐induced obesity, insulin resistance, and nonalcoholic fatty liver disease (NAFLD)." (PMID 37526326, 2023).
osteosarcoma (16 papers, 2021 to 2025). A usually aggressive malignant bone-forming mesenchymal neoplasm, predominantly affecting adolescents and young adults. "The transcriptome-wide m6A sequencing result of chemoresistant osteosarcoma stem cells revealed that over-expression of METTL3 and low METTL14 expression are associated with doxorubicin chemoresistance and stemness of osteosarcoma cells." (PMID 34094986, 2021). "MN1 enhances mRNA stability through m6A methylation modification mediated by METTL14, promoting tumor progression and chemotherapy resistance in osteosarcoma." (PMID 41019085, 2025). "In osteosarcoma, METTL14, highly expressed, prevents the degradation and enhances the translational efficiency of MN1 mRNA through the m6A‐IGF2BP2 axis, contributing to tumorigenicity and conferring all‐trans‐retinoic acid resistance." (PMID 39021049, 2024). "In osteosarcoma, METTL14 facilitated tumor progression by upregulating the m6A modification of MN1 mRNA." (PMID 39054337, 2024). "We found that in osteosarcoma samples with metastasis, METTL14 exhibited significantly decreased expression, and WTAP were significantly differentially expressed." (PMID 34011074, 2021). "METTL3 and ALKBH5 expression levels are upregulated in doxorubicin-resistant osteosarcoma cells, while METTL14 expression is downregulated." (PMID 34094986, 2021). "METTL14 overexpression promotes osteosarcoma cell apoptosis and slows tumor progression through caspase 3 activation." (PMID 34094986, 2021). "In addition, METTL3‐ and METTL14‐mediated m6A modifications of TRIM7 regulate osteosarcoma metastasis and chemoresistance." (PMID 39924638, 2025). "Similarly, METTL14 promotes tumorigenicity and chemoresistance in osteosarcoma by inducing MN1 expression." (PMID 39563370, 2024). "METTL14 exerts a tumor suppressor effect by activating caspase‐3 to constrain the propagation, migration, and aggression of osteosarcoma cells, and is considered a potential target for osteosarcoma treatment." (PMID 34904301, 2022). "Conversely, METTL14 has an inhibitory effect in osteosarcoma." (PMID 34094986, 2021). "Nevertheless, current research on m6A methylation modifications in osteosarcoma has predominantly focused on METTL3, METTL14, WTAP, ALKBH5, and YTHDF2, with few studies on other m6A methylation regulators." (PMID 40176793, 2025). "In osteosarcoma cells, m6A writers, including METTL3, METTL14, WTAP, and KIAA1429 are mostly present in the nucleus." (PMID 34094986, 2021). "METTL3 and METTL14 decrease the RNA level of tripartite motif 7 (TRIM7), while the upregulation of TRIM7 can increase metastasis and the chemoresistance of osteosarcoma by regulating ubiquitination of breast cancer metastasis suppressor 1 (BRMS1)." (PMID 34094986, 2021). "Moreover, there was a significant decrease in demethylase ALKBH5 mRNA inversely correlated with m6A contents in all three osteosarcoma cell lines as compared with hOB cells, but not in METTL3, METTL14, WTAP, and FTO." (PMID 33431791, 2021).
head and neck squamous cell carcinoma (13 papers, 2020 to 2024). A squamous cell carcinoma that arises from any of the following anatomic sites: lip and oral cavity, nasal cavity, paranasal sinuses, pharynx, larynx, and salivary glands. "METTL14 expression was apparently enhanced in Head and Neck squamous cell carcinoma (HNSC) relative to normal tissues." (PMID 38956710, 2024). "METL3 and METTL14 on LNCAROD have tumor-promoting functions in the development of head and neck squamous cell carcinoma." (PMID 34712696, 2021). ", suggesting that the lncRNA RASAL2-AS1/ METTL14/LIS1 axis might be a potential therapeutic target for head and neck squamous cell carcinoma patients." (PMID 38528591, 2024). "METTL3‐mediated and METTL14‐mediated m6A modification enhances the stability of LNCAROD in head and neck squamous cell carcinoma (HNSCC) cells, an effect that is associated with the high expression of LNCAROD in HNSCC." (PMID 34432955, 2021). "Similarly, LNCAROD is up-regulated by METTL3/METTL14 in head and neck squamous cell carcinoma (HNSCC) and impels its tumorigenicity through preventing YBX1 from degradation." (PMID 33754077, 2021). "In head and neck squamous cell carcinoma (HNSCC) cells, the stability of LNCAROD is enhanced through the METTL3 and METTL14-mediated m6A modification." (PMID 33292652, 2020). "Likewise, METTL3- and METTL14-mediated m6A modification of LncAROD enhanced its stability and promoted ternary complex formation with HSPA1A and YBX1, driving progression in head and neck squamous cell carcinoma." (PMID 34458149, 2021). "Meanwhile, METTL14 and WTAP are upregulated in head and neck squamous cell carcinoma (HNSCC), which is instructive for prognostic prediction in HNSCC." (PMID 39289775, 2024). "METTL3/METTL14-induced m6A methylation stabilized LNCAROD in head and neck squamous cell carcinoma (HNSCC) tissue, which augmented malignant cell multiplication and invasion in vivo and in vitro." (PMID 36553003, 2022). "The co-action of METTL3 and METTL14 with m6A modification promotes the stability of lncRNA LNCAROD in head and neck squamous cell carcinoma (HNSCC)." (PMID 36561529, 2022).
cholangiocarcinoma (12 papers, 2022 to 2025). A carcinoma that arises from the intrahepatic biliary tree (intrahepatic cholangiocarcinoma) or from the junction, or adjacent to the junction, of the right and left hepatic ducts (hilar cholangiocarcinoma). "In cholangiocarcinoma, METTL14 induced the expression of seven in absentia homolog 2(Siah2) in cholangiocarcinoma, which in turn promoted PD-L1 expression levels in cholangiocarcinoma." (PMID 39033180, 2024). "The ubiquitination of PD-L1 in cholangiocarcinoma (CCA) is diminished by METTL14 through YTHDF2-mediated inhibition of the RING E3 ubiquitin ligase Siah2, and the deprivation of Siah2 represses T-cell expansion and toxicity by maintaining tumour PD-L1 expression." (PMID 36859310, 2023). "In cholangiocarcinoma (CCA), METTL14 increases m6A modifications in the 3′UTR region of Siah2 mRNA, leading to its degradation via a YTHDF2‐dependent mechanism." (PMID 39802639, 2025). "Paradoxically, METTL14 was proposed to increase sensitivity to anti-PD1 immunotherapy in cholangiocarcinoma (CCA)." (PMID 36810281, 2023). "In this study, we showed that METTL14, a component of the m6A methyltransferase complex, induced Siah2 expression in cholangiocarcinoma (CCA)." (PMID 35154166, 2022). "Similar to NSCLC, in cholangiocarcinoma (CCA), METTL14 binds Siah2 mRNA in the 3′-UTR region and triggers m6A modification, promoting its degradation in a YTHDF2-dependent manner." (PMID 36960074, 2023). "Similarly, METTL14 facilitates the degradation of Siah2 mRNA through m6A modification and YTHDF2-mediated decay in cholangiocarcinoma (CCA)." (PMID 40034695, 2025). "Furthermore, pan‐cancer analysis based on the TCGA database revealed a strong negative correlation between METTL14 and STUB1 expression across most cancers, particularly in cholangiocarcinoma (CCA)." (PMID 40919129, 2025).